FTO (FTO alpha-ketoglutarate dependent dioxygenase)
Diseases named in the same sentence as FTO in open-access papers (continued):
Sharing a sentence is not in itself a finding about the gene and the disease.
Obesity (continued). "Genome-wide association studies have uncovered SNPs in the fat mass and obesity-associated gene (FTO) that are robustly associated with obesity and higher BMI." (PMID 36717943, 2023). "Among the GWAS results, the first obesity-prone locus to be identified was the fat mass obesity-associated (FTO) gene." (PMID 37836016, 2023). "The FTO gene has recently been studied in association with affective disorders given its high abundance in the brain and often comorbid obesity and depression." (PMID 36983683, 2023). "Among the genetic factors, SNPs within the FTO gene have been the most associated with obesity-related phenotypes in GWAS conducted in various populations." (PMID 37709841, 2023). "We found only 14 and 46 genes (8 of them were common in both comparisons) which were expressed more in active or inactive beige adipocytes, respectively, carrying the FTO obesity-risk as compared to the risk-free variant." (PMID 37416800, 2023). "There was a significant interaction between FTO rs9939609 polymorphism and obesity or T2DM on dyslipidemia risk." (PMID 38161971, 2023). "There are several single nucleotide polymorphisms (SNPs) on FTO that has been associated with obesity in different populations." (PMID 37697388, 2023). "Genetic variants of the fat mass and obesity-associated protein, also known as alpha-ketoglutarate-dependent dioxygenase (FTO) gene, which was the first mRNA demethylase identified, have been correlated to obesity and metabolic syndrome." (PMID 37404756, 2023). "Two of the earliest genome-wide association studies in this field showed a correlation of FTO variants with early onset of obesity in a German population and with T2DM in a Finnish population." (PMID 36983642, 2023). "Genetic variants within the FTO gene that exhibit the largest effect size on obesity were found to interact with environmental factors, such as physical activity, diet, alcohol consumption, and sleep duration." (PMID 36966243, 2023). "The sequences of four so-called obesity genes were gathered and analyzed, including FTO (fat mass and obesity-associated protein), PPARG (peroxisome proliferator-activated receptor), ADRB3 (adrenergic receptor 3), and FABP2 (fatty acid-binding protein 2)." (PMID 36717943, 2023). "In eukaryotic cells, FTO acts as an RNA N6-methyladenosine (m6A) demethylase, and the imbalance of m6A has been linked to a variety of human diseases, including obesity, diabetes, heart failure, neurological diseases, and cancer." (PMID 37605223, 2023). "(2007) showed that the intron 1, a common variant of the fat mass and obesity (FTO) gene, is associated with BMI and predisposes individuals to obesity." (PMID 38090689, 2023). "Next, we measured the cellular respiration of the three types of adipocytes carrying FTO risk-free or obesity-risk alleles." (PMID 37416800, 2023). "The landmark 2007 European study initially found that per risk allele in the FTO SNP rs9939609, there was a 1.32-fold increased odds of obesity." (PMID 37664850, 2023). "As a consequence, stimulated maximal and proton leak respiration, which positively correlates with UCP1 activity, and extracellular acidification were suppressed in active beige adipocytes originated from FTO obesity-risk genotype carriers." (PMID 37416800, 2023). "The FTO gene, located at chromosome 16q12.2, encodes for the fat-mass- and obesity-associated protein." (PMID 36839421, 2023). "Genome-wide association studies (GWAS) reveal common polygenic gene variants, for example in the fat mass and obesity-associated (FTO) gene region, that are associated with changes in fat mass and contribute towards the development of obesity." (PMID 36781624, 2023). "The FTO region has the strongest genetic association with obesity, and previous studies have indicated that risk allele carriers for FTO benefit metabolically from healthy behaviors such as physical activity." (PMID 37884680, 2023).
Obesity (continued). "The 19 high-confidence effector genes were enriched for biological pathways related to diet and obesity (response to caloric restriction and FTO obesity variant mechanism) and for regulation of cell differentiation." (PMID 37433298, 2023). "An exciting work from Li and collaborators (2019) described MiR-149-3p as a regulator of MSC fate, inhibiting adipogenesis and favoring osteogenesis; its overexpression decreased obesity-associated gene (FTO) expression." (PMID 36831188, 2023). "Intriguingly, we found that active beige adipocytes carrying FTO obesity-risk genotypes have less distinguishable characteristics as compared to white or inactive beige adipocytes." (PMID 37416800, 2023). "Fat mass and obesity-associated protein (FTO) is an RNA m6A demethylase initially identified as a gene associated with obesity and energy metabolism due to its ability to affect lipogenesis." (PMID 37626050, 2023). "A recent study investigated a polymorphism in the fat mass and obesity-associated gene FTO and found that homozygous AA allele carries showed a smaller meal-induced ghrelin suppression after the same caloric load than TT allele carriers." (PMID 37077276, 2023). "Previous studies have shown that fiber can interact with FTO gene polymorphism to reduce the risk of obesity." (PMID 37571378, 2023). "The FTO polymorphisms rs9939609 (T/A) and rs17817449 (T/G) have been associated with obesity in the Brazilian population." (PMID 37240750, 2023). "The fat mass and obesity-associated (FTO) locus was the first obesity-related GWAS-identified locus and remains the most highly significant and robustly replicated." (PMID 37664850, 2023). "We also revealed that one-carbon metabolism pathway, in which SHMT1 and GPT2 participate, was less expressed in active beige adipocytes with FTO obesity-risk alleles." (PMID 37416800, 2023). "Endothelial FTO loss protected from obesity-induced metabolic and vascular dysfunction by increasing AKT phosphorylation in endothelial cells and skeletal muscle and preserving myogenic tone in resistance arteries." (PMID 37612540, 2023). "Are there race and sex differences in the association of FTO single-nucleotide variants (SNVs) with obesity phenotypes and cardiometabolic disease among self-identified Black and White US residents?" (PMID 38064210, 2023). "Among the many genes known to influence morphometric traits, the FTO (fat mass and obesity-associated) and PLIN1 (perilipin 1) genes have gained attention due to their involvement in adipogenesis and lipid metabolism in the PPAR signaling pathway." (PMID 37835645, 2023). "A study that evaluated FABP2, LEPR, LEP and FTO polymorphisms in individuals who underwent RYGB found that the %EWL was higher in patients with obesity carriers of the LEP variant rs1137101, 12 and 24 months after surgery." (PMID 37129798, 2023). "For example, several studies, such as in US, Norway and Iran, found a significant association between BMI and the fat mass and obesity-associated (FTO) genes in many general population studies." (PMID 38117791, 2023). "Although FTO has long been linked to obesity, an increasing interest in FTO in metabolic regulation has recently emerged." (PMID 36352530, 2023). "Genome-wide association studies identified the strong association between obesity and the Fat mass and obesity-associated (FTO) gene." (PMID 37416800, 2023). "Numerous studies have stated that FTO is associated with obesity in the form of m6A demethylase and plays an important role in lipogenesis and obesity susceptibility." (PMID 36830642, 2023). "The high-confidence genes related to hip osteoarthritis were enriched for the FTO-obesity-variant-mechanism pathway, regulation of lipid localization, and for a biological pathway related to skeletal formation (proximal/distal pattern formation)." (PMID 37433298, 2023).
Obesity (continued). "The fat mass and obesity-associated gene (FTO) encodes an N6-methyladenosine (m6A) demethylase and belongs to the superfamily of Fe (II)- and 2-oxoglutarate-dependnet dioxygenases." (PMID 37375547, 2023). "Each FTO risk allele is associated with a 20–30% increased risk of obesity and a 1–1.5 kg increase in body weight." (PMID 37836016, 2023). "FTO polymorphisms that have been associated withoverweight/obesity and BMI in preschool aged children include rs9939609 andrs17817449." (PMID 39076398, 2023). "(2007), who performed a genome association scan to identify genetic variants associated with obesity, found that FTO genetic variants are associated with increased changes in the individuals' BMI, hip circumference, and body weight." (PMID 38090689, 2023). "Studies on animal models revealed that homeostasis energy and metabolic disturbances in obesity were associated with the functionality of FTO." (PMID 36678138, 2023). "Such a process is a potential mediating pathway between the risk alleles of the FTO gene and obesity." (PMID 37752455, 2023). "The pathway “FTO obesity variant mechanism” is relevant to the T2D phenotype as SNPs in the Fat mass and Obesity-associated (FTO) gene have been found to be associated with adiposity and risk of obesity in multiple populations." (PMID 36979367, 2023). "Fat mass and obesity-associated (FTO) was responsible for the demethylation of m6A modifications and also mediates demethylation of m1A in tRNA." (PMID 36765416, 2023). "A common variant rs9939609 in the FTO gene predisposed to childhood and adult obesity through an additive association with BMI." (PMID 37612540, 2023). "The product of the FTO gene is the fat mass and obesity-associated protein, the first identified RNA demethylase." (PMID 37200795, 2023). "A previous study in mice has demonstrated that exercise training can lead to weaker association between the FTO and the development of obesity." (PMID 37200795, 2023). "Herein, we investigated the function and underlying mechanism of m6A demethylase fat mass and obesity-associated protein (FTO) in OA progression." (PMID 37005694, 2023). "A total of 175 genes including thermogenic markers (UCP2, CKMT2, and CITED1) and 5 BATLAS markers (PPARGC1B, ACO2, ACSF2, NNAT, and DMRT2) were expressed less in active beige adipocytes carrying FTO obesity-risk variant as compared to risk-free carriers." (PMID 37416800, 2023). "An inverse association was found between an increase in body mass index (BMI) and the duration of exclusive breastfeeding (EXBF) among carriers of the risk allele of the fat mass and obesity-associated gene (FTO) rs9939609." (PMID 36729355, 2023). "Findings concerning dietary protein intake and its interaction with FTO gene variants on obesity measures also conflicted in Turkish and Indonesian populations." (PMID 37664850, 2023). "This study aimed to investigate the interaction of the healthy eating index (HEI) and the dietary approach to stop hypertension (DASH) diet scores with FTO polymorphisms in relation to change in obesity traits." (PMID 37697388, 2023). "The fat mass and obesity-associated (FTO) gene, which is highly expressed in the hypothalamus, is closely related to female pubertal development." (PMID 38129517, 2023). "The three-SNP model included brain-derived neurotrophic factor (BDNF)_rs6265, fat-mass- and obesity-associated protein (FTO)_rs1421085, and SEC16B_rs509325." (PMID 36839421, 2023). "Recent studies examined the interactions between obesity, CRC, and obesity-related genetic factors such as fat mass and obesity-associated protein (FTO) genes." (PMID 37543622, 2023). "The fat mass and obesity–associated gene (FTO) is associated with obesity phenotypes, but the association is inconsistent across populations." (PMID 38064210, 2023).
Obesity (continued). "Epidemiologic studies demonstrated that FTO single nucleotide polymorphisms (SNPs) are associated with the increased obesity and higher risk of multiple cancers including colorectal cancer." (PMID 36874096, 2023). "Interactions of FTO rs9939609 polymorphism with obesity and other factors on the risk of T2DM or dyslipidemia." (PMID 38161971, 2023). "Identifying the best posteriori dietary pattern which modifies the association of FTO polymorphisms with obesity can help people adhere preventive recommendations especially in individuals with greater genetic susceptibility to obesity." (PMID 37697388, 2023). "Given that FTO is widely associated with obesity, and changes in appetite and weight are one of the common symptoms in MDD, FTO has been a novel candidate for these studies." (PMID 37047192, 2023). "Another FTO variant rs8061518 in Intron 3 was associated with decreased risk of obesity and low concentration of leptin." (PMID 37612540, 2023). "The fat-mass and obesity-associated (FTO) rs9939609 polymorphism is highly associated with obesity-related metrics across the lifespan and facilitates weight gain by increasing energy-dense food intake, including in children without obesity." (PMID 37145386, 2023). "Several recent studies reported the best target is to inhibit the fat mass and obesity-associated protein (FTO) in obesity therapy." (PMID 36678138, 2023). "The experimental findings discussed in this review fully demonstrate a close relationship of FTO polymorphisms with obesity and the relevant metabolic disorders." (PMID 37375547, 2023). "In 2007, variations in the first intron of the fat mass and obesity-associated gene (FTO) were identified to be associated with increased body mass." (PMID 37223038, 2023). "One SNP was previously associated with obesity, the rs8057044 in the FTO gene, that has also been associated with high BP in a study performed in Tunisian adults." (PMID 37324619, 2023). "Significant interaction between FTO rs17817449 polymorphism and obesity on dyslipidemia risk has been observed." (PMID 38161971, 2023). "This SNP is connected to the FTO gene at chromosome 16, and has previously been (statistically significant) associated with obesity in a large number of genome-wide association studies including different independent data sets." (PMID 36917581, 2023). "Some polymorphisms in the FTO gene (fat mass- and obesity-associated) have been strongly associated with elevated BMI and type 2 diabetes." (PMID 37569198, 2023). "These include the obesity predisposing FTO (fat mass and obesity associated gene) and MC4R (melanocortin 4 receptor) genes related to food intake control (e.g., appetite, eating behavior) and energy homeostasis regulation." (PMID 36875367, 2023). "FTO is one of the strongest genetic loci for obesity and adiposity, and rs56094641 is in linkage disequilibrium (LD) with the obesity signal such that the DKD risk-associated allele is also associated with obesity." (PMID 37324271, 2023). "The strongest association with obesity was found for the FTO (the fat mass and obesity associated gene)." (PMID 37629396, 2023). "Namely, the AA genotype has a higher risk of obesity along with higher FTO methylation levels than the same genotype but with lower levels." (PMID 37200795, 2023). "There were 116 and 158 genes (61 common), which were expressed less in active as compared to inactive beige adipocytes carrying FTO risk-free or obesity-risk alleles, respectively." (PMID 37416800, 2023). "The obesity-promoting allele of FTO is a common polymorphism with a minor allele frequency of 40–45% in European ancestry populations and has a relatively large effect on BMI [0.35 kg/m2 per allele; equivalent to 1 kg for a person who is 1.7 m tall; 2]." (PMID 37223038, 2023). "The fat mass and obesity associated gene (FTO), an RNA demethylase, is downregulated in the hippocampus of patients with MDD and in mouse models of depression." (PMID 37387537, 2023).
Obesity (continued). "GDFD is caused by mutations in the fat mass and obesity-associated gene (FTO) that encodes for an mRNA demethylase." (PMID 36671555, 2023). "Mice with the whole-body knockout or loss-of-function mutation of FTO had reduced adipose tissue and body weight (BW), while transgenic mice overexpressing FTO displayed increased food intake and obesity." (PMID 36352530, 2023). "The fat mass and obesity-associated protein (FTO), encoded by the FTO gene, is implicated in adipocyte dysfunction and obesity development." (PMID 37109044, 2023). "For example, GWAS efforts by others for obesity have shown a pronounced association with variation within the FTO gene that associate with obesity." (PMID 36608130, 2023). "Many diseases are associated with risk alleles of the FTO gene such as metabolic syndrome, diabetes, obesity and cancer." (PMID 37200795, 2023). "In this study, 106 subjects with class I obesity, genotyped with the fat mass and obesity-associated (FTO) rs9930506 gene variant, were enrolled into a 12-week weight loss program (WLP)." (PMID 37626800, 2023). "The FTO gene expresses the fat mass and obesity-associated protein, also known as alpha-ketoglutarate-dependent dioxygenase, which functions to increase energy intake after food deprivation but is accentuated by low physical activity." (PMID 37233716, 2023). "The FTO gene rs9936909 polymorphism is one of the well-documented single nucleotide polymorphisms in the context of increased risk of obesity, including in children." (PMID 37500688, 2023). "Polymorphisms in the fat mass and obesity-associated (FTO) gene are strongly associated with obesity, type 2 DM, and elevated blood pressure." (PMID 37240750, 2023). "The rs9939609 FTO polymorphism is associated with obesity, with more pronounced features as the risk allele increases." (PMID 37200795, 2023). "Given that PCOS is frequently associated with obesity and compromised glucose tolerance, we investigated the prevalence of the rs9939609 variant within the FTO gene among women diagnosed with PCOS and a control group." (PMID 37710301, 2023). "In the White group, 11 FTO SNVs were significantly associated with obesity, hypertension, and diabetes using linear models (eg, body mass index: β = 0.536; 95% CI, 0.197-0.875), but none of the FTO SNVs were associated with obesity traits in the Black group." (PMID 38064210, 2023). "Among them, the strongest susceptibility gene identified is the Fat Mass and Obesity (FTO)-associated gene." (PMID 36979984, 2023). "There were 93 and 130 genes which were expressed less in active beige as compared to white adipocytes carrying FTO risk-free or obesity-risk alleles, respectively." (PMID 37416800, 2023). "FTO was originally identified in genome-wide association studies (GWAS) as having a modest, but significant, contribution to childhood and adult obesity." (PMID 37628704, 2023). "Lower consumption of these amino acids was observed in active beige adipocytes with FTO obesity-risk genotype as compared to risk-free allele carriers." (PMID 37416800, 2023). "The protein-protein interactions of the upregulated and downregulated genes were mapped to form a network, whereinPNLIP (Pancreatic lipase) and FTO (Fat mass and obesity associated protein) gene clusters were visualized as densely connectedclusters in MCODE." (PMID 37808366, 2023). "Mechanistically, we showed that fat mass and obesity- associate gene (FTO)-mediated m6A induced the upregulation of ENST00000436340." (PMID 36792603, 2023). "The fat mass and obesity-associated gene (FTO) encodes an RNA N6-methyladenosine demethylase that regulates RNA stability and molecular functions." (PMID 37375547, 2023). "Our findings suggest a notable correlation between the FTO gene variant rs9939609 and increased obesity prevalence among women of Gujarati ethnicity." (PMID 37710301, 2023).